HMGB1 (high mobility group box 1)
Diseases named in the same sentence as HMGB1 in open-access papers (continued):
Sharing a sentence is not in itself a finding about the gene and the disease.
Sepsis (continued). "Moreover, circTLK1 knockdown repressed sepsis‐induced mtDNA oxidative damage, mitochondrial dysfunction and consequent cardiomyocyte apoptosis by inhibiting PARP1/HMGB1 axis in vitro and in vivo." (PMID 34410682, 2021). "Given that HMGB1 is a late lethality mediator in sepsis, our present findings may support the clinical feasibility of RAGE-aptamer for treatment of severe sepsis." (PMID 34413930, 2021). "Thus, circTLK1 inhibition improved sepsis‐induced oxidative stress damage and mitochondrial dysfunction by inhibiting PARP1/HMGB1 axis." (PMID 34410682, 2021). "HMGB1 added to whole blood at physiological pH did not bind leukocyte receptors, but lowering pH with lactic acid to mimic sepsis conditions allowed binding, implying the presence of natural inhibitor(s) preventing binding at normal pH." (PMID 33658363, 2021). "Numerous molecules serve as DAMPs that initiate and potentiate noninfectious inflammatory responses during sepsis [i.e., high mobility group box 1 (HMGB1), histones, ATP, uric acid, and interleukin]." (PMID 34257519, 2021). "Anti-HMGB1 antibodies alter inflammation in murine sepsis model and reduce sepsis mortality without potentiating immunosuppression." (PMID 33925132, 2021). "DG has been reported to effectively inhibit bacterial endotoxin–induced HMGB1 release in vitro and help mice defend against lethal endotoxemia and CLP-induced sepsis, and inhibit pro-inflammatory mediators IL-1β and TNF-α, thereby protecting LPS-induced endotoxic shock in rabbits." (PMID 34938184, 2021). "Nonetheless, we are aware that this result does not provide direct evidence that extracellular HMGB1 originates from necroptosis in sepsis." (PMID 33947887, 2021). "Extracellular HMGB1 functions as a proinflammatory cytokine in a Toll-like receptor- (TLR) and receptor for advanced glycation end-products (RAGE)-dependent manner in severe sepsis and autoimmune diseases." (PMID 34830606, 2021). "Serum HMGB1 levels are increased in septic patients as compared to healthy subjects, the highest levels were observed in non-surviving septic patients, identifying HMGB1 as a valuable clinical marker of sepsis severity/progression." (PMID 34685561, 2021). "In a murine sepsis model involving cecal ligation and puncture (“CLP”), the elevated serum HMGB1 levels peaked 3 to 4 weeks postinjury and only returned to baseline levels by week 12; associated with these changes, the mice exhibited a significant decline in spatial memory for up to four months." (PMID 34685561, 2021). "Without any doubt, HMGB1 is a crucial mediator for the innate immune system and an attractive target for therapy in many disease states, including sepsis, ischemia, arthritis, autoimmune diseases, neurodegenerative diseases, metabolic disorders and cancer." (PMID 33807604, 2021). "HMGB1 oxidation is the major PTM that drives secretion and its oxidized form of extracellular HMGB1 induce inflammatory signaling, which leads to many diseases, including neuroinflammation, hyperalgesia, drug-induced liver injury, and sepsis." (PMID 32587593, 2020). "HMGB1 levels were unchanged in all patients, even when the patients were divided into those with and without sepsis." (PMID 32635454, 2020). "In addition to TLRs stimulation, other inflammatory mediators have been identified in sepsis such as C5a, MIF, HMGB1 and IL17-A1,4." (PMID 33139717, 2020). "In addition, HMGB1/PTEN/β-catenin signaling is a novel pathway that regulates the regulatory T-cell (Treg) development and provides a potential therapeutic target in sepsis-induced lung injury." (PMID 32412059, 2020). "In sepsis-induced animal model of lung damage, study show that the protective role of Xuebijing (XBJ) may be via inhibiting HMGB1/RAGE axis to decrease pro-inflammatory cytokines releases." (PMID 33552058, 2020).
Sepsis (continued). "Although initial studies demonstrated HMGB1 was a late mediator of sepsis, recent findings indicate HMGB1 plays an important role in models of non-infectious inflammation, such as autoimmunity, cancer, trauma, and ischemia reperfusion injury." (PMID 33114371, 2020). "Heme pre-treatment was shown to protect mice from lethal endotoxemia and sepsis induced by LPS or CLP, respectively, and this effect was related in part to reduction of pro-inflammatory cytokines and normalization of high mobility group box-1 (HMGB1) protein levels." (PMID 33228260, 2020). "Extracellular HMGB1 has been shown to be critical for ALI associated with both sterile (e.g., trauma) and nonsterile (e.g., sepsis) insults." (PMID 33293898, 2020). "Therefore, sesamin pre-treatment effectively attenuated the HMGB1/TLR-4/IL-33 signalling pathway, which was enhanced by sepsis." (PMID 32893702, 2020). "They measured HMGB1 in sepsis nonsurvivors and survivors using two different (non-commercial) methods." (PMID 31705327, 2019). "Thus, it can be deduced that the inflammatory action of MLN DCs in sepsis, via IL-1β, is dependent upon mediation via TLR4 and/or HMGB1." (PMID 31323786, 2019). "Additionally, evidence shows that the administration of Gln inhibits HMGB1 through increased expression of heat shock protein (HSP) 70 and, consequently, reduces lung damage in sepsis-induced lung injury." (PMID 31013737, 2019). "Furthermore, HMGB-1 has been positively correlated with percent TBSA, to be higher in non-surviving burn patients, and elevated in those suffering from sepsis." (PMID 31998665, 2019). "Blockade of HMGB1 or macrophage PTEN deletion activates PI3K/PDK1/Akt and β-catenin signaling, which in turn enhances macrophage TGF-β leading to increased Foxp3 Treg induction while inhibiting Th17 cell differentiation during sepsis-induced lung injury." (PMID 31402909, 2019). "In the present study, the clearance rates of β-globin, HSP70, and HMGB1 were higher in all non-surviving AKI patients with sepsis (P = 0.006, P = 0.005, and P = 0.000, respectively)." (PMID 30666251, 2018). "Other studies have not confirmed the prognostic value of HMGB-1 in GDV syndrome or sepsis however, suggesting that the value of this biomarker varies with the population, the illness severity and the nature of the disease process." (PMID 30105229, 2018). "HMGB1 is a nuclear histone binding protein that upon its release acts a DAMP, and has been identified as a critical mediator of mortality in peritoneal and endotoxin-induced sepsis." (PMID 29601597, 2018). "Concentrations of HMGB-1 are increased in dogs with gastric dilation-volvulus (GDV), dogs with sepsis, and correlate with plasma nucleosome concentrations in critically ill horses, suggesting it may provide information about tissue injury in dogs with trauma." (PMID 30105229, 2018). "Thus, we neutralized cerebral HMGB1 right after CLP surgery, and found improvements on activities and memory of mice undergone sepsis." (PMID 29190939, 2017). "In this study, we found that GL could protect rats against lethal sepsis induced by CLP and suppress the production of HMGB1 and proinflammatory cytokines in septic rats." (PMID 28484719, 2017). "As far as we know, previous studies mainly focused on down-regulating the release and the action of peripheral HMGB1, but without any reports on antagonizing central HMGB1 directly in sepsis settings." (PMID 29190939, 2017). "Importantly, VEGF neutralization with soluble fms-like tyrosine kinase 1 (sFLT-1) (a soluble VEGF receptor) and HMGB1-neutralizing antiserum attenuated other organ injury including the liver and lungs and improved the survival of CKD-sepsis animals." (PMID 27011788, 2016). "High-mobility group box 1 (HMGB1), an important late inflammatory cytokine during inflammation, participates in the pathogenesis of systemic inflammation and local inflammations, including sepsis and rheumatoid arthritis." (PMID 27413250, 2016).
Sepsis (continued). "Several basic studies have demonstrated that HMGB1 neutralizing therapy improves mortality of sepsis in non-CKD mice." (PMID 27011788, 2016). "Septic patients have significantly increased serum HMGB1 levels, which can induce endothelial cell hyperpermeability via BAX and BCL-2 regulated apoptosis, EP can reverse these detrimental effects to prevent endothelial cell injury in experimental sepsis." (PMID 27980458, 2016). "Here the authors show this switch drives IL-1β, IL-18 and HMGB1 release from macrophages by activating the NLRP3 and AIM2 inflammasomes via protein kinase R phosphorylation, a pathway that can be inhibited to prevent sepsis in mice." (PMID 27779186, 2016). "Through its immune modulating properties, HMGB1 plays an important role in autoimmune diseases like rheumatoid arthritis (RA) and systemic lupus erythematosus (SLE), as well as in acute inflammatory events like sepsis and trauma." (PMID 26854151, 2015). "Although stearoyl LPC significantly attenuates circulating high-mobility group box 1 (HMGB1) levels in endotoxemia and sepsis by suppressing the release of endotoxin-induced HMGB1 from macrophages/monocytes, there has been no report of the antioxidative activity of LPC." (PMID 26275144, 2015). "Targeting HMGB1 rather than early response cytokines provides a wider time window for clinical intervention to prevent lethal sepsis." (PMID 25904867, 2015). "Therefore, kallistatin protects against sepsis-induced inflammation, organ damage and mortality by antagonizing TNF-α- and HMGB1-mediated inflammatory gene expression, and by inducing SOCS3 synthesis." (PMID 25930108, 2015). "In addition to inhibiting HMGB1 release in sepsis, activation of the NRF2-HO1 pathway also limits HMGB1 release and protects against I/R injury and other sterile inflammatory injuries." (PMID 25904867, 2015). "Although the underlying pathophysiology of sepsis has not been completely elucidated, TNF-α and HMGB1 upregulation is known to play a crucial role in the systemic inflammatory response." (PMID 25930108, 2015). "Unlike in sepsis, HMGB1 levels are increased as early as 1 h after I/R injury and then increase in a time-dependent manner for up to 24 h." (PMID 25904867, 2015). "Liberation of the archetypal endogenous DAMP, the non-histone DNA binding molecule High Mobility Group Box 1 (HMGB1), has been shown to play a critical role in a variety of inflammatory disorders including sepsis, trauma, cancer and autoimmunity." (PMID 25706559, 2015). "While extracellular HMGB1 also participates in many biological processes, such as immunomodulatory role of sepsis or noninfectious inflammation, angiogenesis, wound healing, and tumorigenesis." (PMID 24510323, 2014). "High-mobility group box 1 (HMGB1) protein is one of the most important pro-inflammatory cytokines secreted by reactive astrocytes, and mediates a variety of inflammatory responses following insults that include sepsis, pancreatitis and pneumonia." (PMID 24970310, 2014). "Although treatment of severe sepsis and septic shock with awareness of measures against pro-inflammatory cytokines and high mobility group box 1 (HMGB-1) proteins is common in Japan, such a method is not widely used in Europe and the United States." (PMID 25705413, 2014). "This study suggests that, unlike sepsis models, HMGB1-based interventions directed at the specific epitope targeted by anti-HMGB1 2G7 are not likely to be efficacious in the prevention of experimental SM in PbA-infected C57BL/6 mice." (PMID 23506269, 2013). "HMGB1 is not detectable in serum of normal subjects, but it is significantly increased in clinical inflammatory conditions such as sepsis, rheumatoid arthritis, and chronic kidney disease." (PMID 23359306, 2013).
Sepsis (continued). "The therapeutic potential of anti-HMGB1 antibody, soluble RAGE, and anti-RAGE neutralizing antibody has been demonstrated in experimental sepsis, liver ischemia/reperfusion injury, Con-A-induced hepatic injury, traumatic brain injury, and organ transplantation." (PMID 23690821, 2013). "Administration of anti-HMGB1 antibody was effective to alleviate both sepsis-induced and non-sepsis-induced organ injury." (PMID 23532259, 2013). "The pathogenesis of sepsis involves a complex process of cellular activation at multiple levels resulting in release of pro-inflammatory cytokines such as TNF-α, IL-1β, high-mobility group box 1(HMGB1) and anti-inflammatory cytokines, such as IL-10." (PMID 23497622, 2013). "The present study did not clarify the exact mechanisms by which expression of HMGB1 in the nucleus produced vascular hyporeactivity during sepsis." (PMID 23532259, 2013). "In this study, we found that serum HMGB1 levels were 10-fold higher in patients with sepsis than normal controls." (PMID 24062788, 2013). "In striking contrast, caPI3K mice, subjected to CLP sepsis, showed no significant translocation of HMGB-1 from the nucleus to the cytoplasm." (PMID 23028587, 2012). "In addition, LPS-treated mice developed increased serum levels of HMGB1, similar to human patients with sepsis, suggesting that HMGB1 is a DAMP molecule in regard to sepsis symptoms." (PMID 23316484, 2012). "The pathogenesis of sepsis is rather complex, but is partly mediated by endotoxin, which stimulates macrophages/monocytes to sequentially release early (e.g., TNF, IL-1, IFN-γ) and late (e.g., HMGB1) proinflammatory mediators." (PMID 23193422, 2012). "From our data, however, we conclude that HMGB-1 serum levels do not reflect the course of monocytic immunity in patients with sepsis-induced immunosuppression receiving a specific immunotherapy for this clinical condition." (PMID 20652004, 2010). "HMGB1 levels in infected patients without SIRS did not statistically significantly differ from those with sepsis or sever sepsis." (PMID 20158885, 2010). "Also, other molecules, including high-mobility group box 1 (HMGB-1), have a pivotal role in the innate immune response to diseases, including sepsis." (PMID 20470406, 2010). "In our study levels of HMGB1 were not statistically higher in sepsis patients and HMGB1 did not enable to detect bacteraemia in children." (PMID 20158885, 2010). "In conclusion, our data demonstrate that HMGB-1 serum levels do not reflect monocytic function in patients with sepsis-induced immunosuppression receiving immunostimulatory treatment." (PMID 20652004, 2010). "In contrast to the data reported for sepsis, we found a significant difference in plasma levels of HMGB1 between survivors and non-survivors from severe trauma." (PMID 19887013, 2009). "HMGB-1 is a highly conserved nonhistone DNA-binding protein found in virtually all nucleated cells and is regarded as being the late mediator of sepsis." (PMID 19841752, 2009). "In a more recent study, Gibot and colleagues reported that plasma levels of HMGB1 measured at day three after onset of severe sepsis discriminated survivors from non-survivors." (PMID 19887013, 2009). "HMGB1 levels were significantly higher among infected patients without SIRS compared with those in the healthy control group, and were significantly higher among severe sepsis patients compared with sepsis patients (P < 0.0001)." (PMID 17625012, 2007). "The purpose of the present study was to describe levels of HMGB1 in a non-critically ill population of patients suspected of having sepsis." (PMID 17346334, 2007). "Levels of HMGB1, PCT and LBP were higher in infected patients compared with those in healthy controls, and levels were higher in severe sepsis patients compared with those in sepsis patients." (PMID 17625012, 2007).
Sepsis (continued). "The pathogenesis of sepsis is mediated in part by bacterial endotoxin, which stimulates macrophages/monocytes to sequentially release early (e.g., TNF, IL-1, and IFN-γ) and late (e.g., HMGB1) pro-inflammatory cytokines." (PMID 17987129, 2007). "Although it was reported that extracellularly released HMGB1 is critical for the promotion of sepsis inflammation in response to non-periodontal bacterial LPS, our understanding of the crosstalk between HMGB1 and P. gingivalis-derived virulence lipids remains limited." (PMID 41355213, 2025). "Furthermore, the plasma levels of necroptosis mediators, including high‐mobility group box‐1 (HMGB1), receptor‐interacting kinase 3 (RIPK3) and mixed‐lineage kinase domain‐like (MLKL) proteins, were well correlated with the severity and mortality in sepsis." (PMID 40318009, 2025). "In sepsis-induced AKI models, PKM2 inhibition attenuates the activation of NLR family pyrin domain containing 3 (NLRP3) and absent in melanoma 2 (AIM2) inflammasomes, decreases the release of IL-1β, IL-18, and HMGB1 by macrophages, and ultimately improves survival outcomes." (PMID 40843128, 2025). "Furthermore, the effectiveness of rhsTM in sepsis-induced DIC has been reported based on its anti-inflammatory action through the lectin-like domain, resulting in inhibition of lipopolysaccharide (LPS) and regulation of high mobility group box 1 (HMGB1)." (PMID 40230734, 2025). "In sepsis, the NOD-like receptor family pyrin domain containing 3 (NLRP3) inflammasome leads to the cleavage of Caspase 1 (the typical pathway) or Caspase 11 (the atypical pathway), thereby releasing interleukin (IL)-1β, IL-18, and HMGB1, and leading to pyroptosis." (PMID 38734709, 2024). "Moreover, in sepsis, the interactions of TIM-3 with its ligands, such as Galectin-9, HMGB1, or CEACAM1, may play a crucial role in modulating immune responses and influencing the outcome of sepsis." (PMID 38576606, 2024). "Berberine-mediated blockade of HMGB1/receptor for advanced glycation end products signaling reduces the expression of TNF-α, IL-1α, and complement C1q A chain in the hippocampus of CLP mice, inhibits the activation of microglia, and thus alleviates sepsis-induced cognitive impairment." (PMID 38734709, 2024). "High mobility group box 1(HMGB1) is a highly conserved non-histone chromatin associated protein that largely contributes to the pathogenesis of chronic inflammatory and autoimmune diseases such as sepsis, atherosclerosis, and chronic kidney diseases." (PMID 39840112, 2024). "In addition, miR-205 improved renal cell apoptosis via the HMGB1-PTEN pathway, which might provide a new target for the therapy of sepsis-induced renal injury." (PMID 36874972, 2023). "HMGB-1 showed a relatively constant concentration in the plasma of septic patients, with a T0 level above that of non-septic and sepsis-induced MODS patients, decreasing at T1 below the levels of the sepsis-induced MODS group of patients and maintaining similar levels at T2." (PMID 37441100, 2023). "During sepsis (resulting from severe infection mostly with Gram-negative bacteria), platelets become overactivated and release PEVs containing numerous molecules and DAMPs, such as HMGB1, proinflammatory cytokines (IL-1β, TNF-α, IL-6) and chemokines (MCP-1)." (PMID 37559007, 2023). "To determine whether Erbin-mediated autophagy regulates sepsis-induced inflammatory response and organ injury, we investigated the level of inflammatory cytokines TNF-α, IL-6, IL-1β, HMGB1, and IL-10 in polymicrobial sepsis mice and MDP-treated BMDMs with CQ treatment." (PMID 38105228, 2023). "In the human sepsis, the serum HMGB1 is increased, especially in non-survivors." (PMID 36776867, 2023). "It has been reported that lactylated HMGB1 increases and is secreted by macrophages via exosomes and promotes endothelial cell permeability under septic conditions, which declared that lactylation also impacts sepsis in a non-histone way." (PMID 36774341, 2023).